GADD45B (growth arrest and DNA damage inducible beta)
Diseases named in the same sentence as GADD45B in open-access papers (continued):
Sharing a sentence is not in itself a finding about the gene and the disease.
tumor (continued). "Therefore, we infer that GADD45B may also be regarded as a potential tumor progression predictive marker in CRC." (PMID 30029519, 2018). "In conclusion, our findings highlight GADD45B as a key regulator in SKCM progression, capable of restraining tumor cell proliferation and enhancing apoptosis." (PMID 40350499, 2025). "Our single-cell RNA sequencing and immune correlation analysis revealed that GADD45B expression positively correlates with macrophage activation, particularly M1 polarization, suggesting that it may augment the efficacy of ICIs by fostering a more immunogenic tumor microenvironment." (PMID 40350499, 2025). "Patients with LUAD with higher levels of expression of GADD45B and PPP3CC exhibited better survival outcomes, suggesting that GADD45B and PPP3CC indeed exhibit a tumor-suppressive effect." (PMID 38167059, 2024). "From the perspective of reducing oncogenesis, inhibiting Gadd45β as a method for preventing HCC oncogenesis has limited prospects and acceptance compared with post‐tumour intervention treatment." (PMID 39653679, 2024). "Within the tumor microenvironment, GC cells with high GADD45B expression are prominently involved in the CD99 signaling network, while those with low GADD45B expression predominantly participate in the CDH signaling network." (PMID 37608794, 2023). "On the other hand, GC cells with low GADD45B expression participate in the primary CDH signaling pathway network and interact with other tumor cells, fibroblasts, and vascular endothelial cells via CDH1-CDH1 ligand receptors." (PMID 37608794, 2023). "Seven genes of the prognostic model (COPA, GPX7, ITGB5, MATN3, MCM7, MMP1, and SPP1) have been validated to be related to tumor progression, whereas the remaining three genes, BNDF, GADD45B, and LOX, need to be further analyzed." (PMID 35699863, 2022). "Sodium selenite treatment upregulated pro-apoptotic, apoptotic, and tumor suppressor genes such as ATF3, FOSB, GADD45B, DUSP8 and ACHE, and downregulated tumor cell survival genes such as SCD, LRP1, RAB31, SRPX2, PDK1 and CSGALNACT1." (PMID 36059619, 2022). "Some NF-κB target genes such as CCND1, BCL2L1 and GADD45B and ICAM1 which are responsible for proliferation, anti-apoptosis and adhesion were also upregulated in the tumor tissues." (PMID 33144684, 2021). "As shown in the volcano plot, SU decreased GZMB expression and upregulated genes related to inflammatory activation (FOS, JUN, NFKBIA, DUSP2, JAK1, PIM1), tumor immunity (CD47, PCBP2, EIF5A, PDIA3, EGR1), and DNA damage (H2AFX, DDIT3, GADD45B)." (PMID 34824394, 2021). "Taken together, the results suggest that GADD45B and PMAIP1, when negatively regulated by TFAP2C, can act as tumor suppressive factors inhibiting NSCLC tumorigenesis." (PMID 31296259, 2019). "We firstly examined Gadd45β expression in one hundred of HCC cases and peri-tumor tissues by immunohistochemistry (IHC) staining." (PMID 29225771, 2017). "Firstly, the expression of Gadd45β in one hundred cases of HCC and surrounding peri-tumor tissues were studied." (PMID 29225771, 2017). "Mechanistically, the observed synergistic anti-tumor effect is mediated through the simultaneously silencing of ACSL4 and induction of GADD45B expression in HCC cells." (PMID 28900541, 2017). "The present analysis showed, for the first time, that the anti-tumor effect of fisetin was mediated mainly through activation of CDKN1A, SEMA3E, GADD45B and GADD45A and down-regulation of TOP2A, KIF20A, CCNB2 and CCNB1 genes." (PMID 28052097, 2017). "Moreover, inhibitor of growth, i.e. Tgfb1, Gadd45b, Igfbp6, A-kinase-anchoring protein (Akap12) and protein tyrosine phosphatase, non-receptor type substrate 1 were highly significantly repressed, from which their important role in tumor progression can be inferred." (PMID 29254206, 2017).
tumor (continued). "Together, our results suggested that during the process of acute I/H, SAMe increased GADD45β expression and consequently activated apoptosis in HCC cells to suppress tumor proliferation." (PMID 27177086, 2016). "GADD45B shares the common functions of the GADD45 family, including the regulation of cell growth, cell apoptosis, cellular responses to DNA damage and anti-tumor immune responses." (PMID 23110778, 2012). "In contrast, Taxotere and/or Furtulon up-regulated some genes that are related to the induction of apoptosis (GADD45A, GADD45B, etc), cell cycle arrest (p21CIP1, VDUP1, BTG, etc), and tumor suppression." (PMID 15656911, 2005). "Previous GO and KEGG analyses showed that GADD45B may be related to the development of SKCM, so we further analyzed the correlation between GADD45B and tumor-related processes." (PMID 40350499, 2025). "The current strategies favour upregulating Gadd45β to enhance tumour apoptosis rather than inhibiting its function to suppress tumour growth in HCC treatment." (PMID 39653679, 2024). "Therefore, the Gadd45b ablation in macrophages re-establishes proinflammatory TAM activation and CD8+ T-cell infiltration into the tumor, thus inhibiting ovarian adenocarcinoma growth." (PMID 38397187, 2024). "Unfortunately, no drugs have used this as a target to inhibit tumour growth or prevent tumour progression by inhibiting the function of Gadd45β." (PMID 39653679, 2024). "It has been reported that GADD45B and PMAIP1 have significant roles in anti-proliferation and apoptosis, suggesting that they may function as tumor suppressors." (PMID 31296259, 2019). "We propose that GADD45B and PMAIP1 be considered putative tumor suppressive factors in NSCLC that might be useful as prognostic markers during NSCLC therapy." (PMID 31296259, 2019). "This study indicates that GADD45B and PMAIP1 could be promising tumor suppressors for NSCLC and might be useful as prognostic markers for use in NSCLC therapy." (PMID 31296259, 2019). "The present analysis showed, for the first time, that the anti-tumor effect of fisetin was mediated mainly through modulation of multiple signaling pathways and via activation of CDKN1A, SEMA3E, GADD45B and GADD45A and down-regulation of TOP2A, KIF20A, CCNB2 and CCNB1 genes." (PMID 28052097, 2017). "Mechanistic studies demonstrated that combining sorafenib and aspirin yielded significant synergistically anti-tumor effects by simultaneously silencing ACSL4 and the induction of GADD45B expression in HCC cells both in vitro and in the orthotopic HCC xenograft mouse model." (PMID 28900541, 2017). "Until now, the GADD45 gene family, including GADD45A, GADD45B and GADD45G, has been recognized as stress sensors that modulate the response of mammalian cells to genotoxic and physiological stresses and the process of tumor formation and progression." (PMID 23110778, 2012). "GADD45B expression was not correlated with patients’ sex, age, tumor size, location, gross type, differentiation and TNM stage." (PMID 23110778, 2012). "Expression of GADD45B in CRC was abnormal; this gene may lose its normal functions as a tumor suppressor gene." (PMID 23110778, 2012). "A total of 56 molecules are annotated as affecting neoplasia and eight of these are dysregulated over 1.5 fold in Ad12-TC compared to Ad5-TC: down-regulation of ATM, CD19, CD3G, GADD45B, HPSE, TFAP2A and TFPI was observed, whereas levels of EGFR were found to be up-regulated." (PMID 19200380, 2009). "Thus, we can simply assume that Gadd45β has the function of promoting cell apoptosis and therefore can inhibit tumours, whereas the subsequent effect of binding with CAR promotes liver regeneration and tumour development." (PMID 39653679, 2024). "In addition, we believe that the role of GADD45B in promoting the prognosis should not be limited to promoting chemotherapy sensitivity, because many studies have shown other effects, such as tumor immunity." (PMID 34490266, 2021).
tumor (continued). "Significantly, DTP3 displayed potent and selective activity in both MM and non-MM cell lines exhibiting high levels of GADD45B expression, whereas it was completely inactive, even at high micromolar concentrations, in tumor cell lines featuring low GADD45B expression." (PMID 25314077, 2014). "In a panel of tumor cell lines of different tissues of origin, the sensitivity to DTP3-induced killing correlated with a very high degree of significance with the mRNA levels of GADD45B, which our data have shown is a pivotal NF-κB-regulated inhibitor of MKK7/JNK signaling and apoptosis in MM cells." (PMID 25314077, 2014). "Expression of GADD45B or GADD45G was not significantly different between the tumor groups." (PMID 17280610, 2007). "Notably, the effects of GADD45β are in line with emerging models of sublethal necroptosis, in which partial activation of RIPK3 promotes sustained NF-κB signaling, whereas its complete activation toward full necroptosis leading to a more immunogenic tumor environment." (PMID 41354733, 2025). "Similarly, GADD45B expression did not exhibit significant differences in relation to the AJCC-metastasis stage and AJCC-tumor stage, but it did show a positive correlation with the AJCC-publication version." (PMID 40350499, 2025).
infection (18 papers, 2012 to 2025). The state of being infected such as from the introduction of a foreign agent such as serum, vaccine, antigenic substance or organism. "NF-κB target genes (i.e., C3, Chi3l1, Fas, Gadd45β, Hmox1, Ptx3, Saa3, Tlr2) were also abundant in DEGs in which upregulation during infection was impaired by CCR5-deficiency." (PMID 31506064, 2019). "In addition, NF-κB target genes (i.e., C3, Chi3l1, Fas, Gadd45β, Hmox1, Ptx3, Saa3, Tlr2) were abundant in the DEGs in which upregulation during infection was impaired by CCR5-deficiency." (PMID 31506064, 2019). "Mechanistically, we observed time-dependent upregulation of TGF-β1 and its downstream effector GADD45b during infection, with subsequent induction of the pro-apoptotic factor BAX." (PMID 40879372, 2025). "GADD45b expression was concomitantly upregulated throughout infection but was markedly suppressed by SB431542 treatment, suggesting that SB431542 inhibits apoptosis via suppression of canonical Smad2/3 signaling and GADD45b expression." (PMID 40879372, 2025). "Gadd45β increased in infiltrating lymphocytes, fibroblast‐like cells and hepatocytes with infection of alveolar echinococcosis." (PMID 39653679, 2024). "A noticeable exception was represented by GAS5 and GADD45b, whose expression levels increased overtime, pointing to growing cell stress during the course of infection, likely initiating cell apoptosis at the later time point of this analysis." (PMID 36768954, 2023). "Recent studies have found that GADD45B is related to the repair of tissues damaged by oxidative stress, ionizing radiation, and infection." (PMID 36978948, 2023). "CCAAT/enhancer-binding protein beta (C/EBPB), growth arrest and DNA-damage-inducible 45 beta (GADD45B), and BCL2, which are associated with cell proliferation and apoptosis, were upregulated at different time points after PCV2 infection." (PMID 35324828, 2022). "Gadd45b has been reported to play a role in modulating inflammation in mice and be induced upon infection by Piscirickettsia salmonis, and infectious salmon anemia virus in the head kidney and liver, respectively, of Atlantic salmon." (PMID 30390635, 2018). "Gadd45β mRNA expression was increased from day2 (∼1.27-fold) to 360 (∼1.81-fold); it peaked at day 90 (∼3.28-fold) post-infection." (PMID 22253905, 2012). "Taken together, these observations suggest that activation of ERK1/2, Gadd45β and Cyclin A are able to interact and promote hepatocyte anti-apoptosis at the middle stage of infection." (PMID 22253905, 2012). "In T cells, Gadd45b is a critical mediator for Th1 response to infection." (PMID 32526449, 2020). "Furthermore, increased expression levels of GADD45β were discovered in cells following the infection with ALV-J, and ALV-J infection was observed to activate the p38MAPK/JNK signaling pathway." (PMID 32826872, 2020). "Western blotting showed increased Gadd45β expression from day60 (∼1.75-fold) to 360 (∼2.52-fold); it peaked at day180 (∼62.64-fold) post-infection; there was a significant difference between E. multilocularis-infected and non-infected mice at days 60 and 180 (P < 0.05)." (PMID 22253905, 2012). "Interestingly, the expression levels of autophagy-related proteins of LC3II (P < 0.01) and Atg5 were definitely increased (P < 0.001), while SQSTM1 were significantly decreased (P < 0.05) following the infection with ALV-J or the overexpression of GADD45β for 4 h in DF-1 cells or CEF cells." (PMID 32826872, 2020). "How might viruses benefit from maintaining the expression of IL-6 and GADD45B during infection?" (PMID 28841715, 2017). "To further characterize the temporal dynamics of apoptosis during infection, we examined expression of BAX, a pro-apoptotic factor regulated by GADD45b." (PMID 40879372, 2025).
infection (continued). "The IPA network analysis revealed that infection induced aged GF(P22)-specific DEGs were connected to each other and the upregulated genes (Id1, KLF10, GADD45b, and CSRNP1) were all mainly localized in the nucleus." (PMID 29190775, 2017). "GADD45B was stable over time, and ATF4 had minor changes starting at 3 h post-infection." (PMID 36768954, 2023). "Furthermore, anti-apoptotic genes, GADD45B and CFLAR, and the IAP family members (BIRC2 and BCL2L1) were upregulated early or late after DTMUV infection." (PMID 32897243, 2020). "Our temporal analyses revealed that at later infection stages (36–48 hours post-infection [hpi]), SARS-CoV-2 exploits TGF-β-induced lysosomal membrane permeabilization (LMP) and apoptosis for viral release—processes effectively inhibited by SB431542 through suppression of GADD45b and BAX expression." (PMID 40879372, 2025).
kidney disease (3 papers, 2016 to 2020). "In summary, Gadd45β plays an important role in the progression of kidney disease." (PMID 32570293, 2020).
neurological diseases (3 papers, 2022 to 2024). "In summary, Gadd45b is widely expressed in the central nervous system, plays a vital role in various nervous system diseases, and is a potential target for the treatment of various nervous system diseases." (PMID 36311022, 2022). "Studies have demonstrated that Gadd45b might be critically involved in neuroinflammation related neurological diseases." (PMID 35721719, 2022).
metabolic disease (2 papers, 2017 to 2023). A congenital disorder (due to inherited enzyme abnormality) or acquired (due to failure of a metabolically important organ) disorder resulting from an abnormal metabolic process. "Studies have shown that GADD45B plays a regulatory role in liver-related metabolic diseases." (PMID 37405258, 2023). "Particularly, the reduced Gadd45b expression in fasting found in MLP pups might be related to the development of metabolic disorders." (PMID 28852200, 2017).
psychiatric disorder (2 papers, 2022 to 2024). A disorder characterized by behavioral and/or psychological abnormalities, often accompanied by physical symptoms. "Further investigation, through siRNA-mediated knockdown of GADD45β expression in the amygdala of neonatal rats, revealed that GADD45β knockdown altered the social behavior of neonatal rats while concurrently reducing the expression of several genes associated with psychiatric disorders." (PMID 38332860, 2024). "Patients with psychiatric disorders were shown to have increased Gadd45b-stained cells in prefrontal cortex layers II, III, and V. This research demonstrated that individuals with psychiatric disorders bind less Gadd45b to the BDNF promoter." (PMID 36311022, 2022). "However, in the frontal cortex layers II, III, and V of individuals with psychiatric disorders (including 15 cases of SCZ and 11 cases of BD), there is an increase in GADD45β-positive cells." (PMID 38332860, 2024).
central nervous system disorder (1 paper, 2024). A disease involving the central nervous system. "This variability underscores the multifaceted biological functionality of GADD45β in the development of central nervous system disorders, with this diversity closely linked to its role in DNA methylation." (PMID 38332860, 2024). "GADD45β displays differential expression in the majority of central nervous system disorders." (PMID 38332860, 2024). "It is noteworthy that GADD45β in SCZ may selectively propel an upregulation in the expression levels of genes associated with BDNF, indicating a potential regulatory role of GADD45β in the demethylation process of critical genes implicated in central nervous system disorders." (PMID 38332860, 2024).
inflammation (1 paper, 2023). Aberrant reaction of the microcirculation characterized by movement of fluid and leukocytes from the blood into extravascular tissues. "Gadd45b, the growth arrest and DNA-damage-inducible gene, can promote adipose inflammation in mice, and its decrease may result in the inhibition of the p38 MAPK pathway." (PMID 37569347, 2023).
GADD45B also shares sentences with these, for which no sentence is quoted: lupus (4 papers); lymphoma (4); Ureteral obstruction (2); anemia (1); Anxiety (1); autism spectrum disorder (1); bacterial infections (1); basal cell carcinoma (1); bladder cancer (1); Burkitt lymphoma (1); cardiovascular disease (1); chronic endometritis (1); chronic obstructive pulmonary disease (1); colorectal adenocarcinoma (1); dementia (1); diabetic kidney disease (1); Embryonic Carcinoma (1); fibrosis (1); germ cell cancers (1); germ cell tumor (1); glomerulopathies (1); head and neck cancer (1); hepatitis B (1); HTLV infection (1); IgA nephropathy (1); Infertility (1); intervertebral disc degeneration (1); leiomyosarcoma (1); memory impairment (1); metastatic disease (1).
A further 17 diseases each share a sentence with GADD45B in 1 paper.